FGFR1 (fibroblast growth factor receptor 1)
Diseases named in the same sentence as FGFR1 in open-access papers (continued):
Sharing a sentence is not in itself a finding about the gene and the disease.
tumor (continued). "The high degree of spatial heterogeneity observed for SNVs in druggable target genes is exemplified by the ALK R1275Q mutation only being detected in 2 of 7 locations in the relapse tumour, the BRAF V600E mutation in only 3 of 7 locations and the FGFR1 N557K mutation in only 5 of 7 locations." (PMID 34815394, 2021). "The comprehensive GEM ExTra® report filtered out the BRCA1 (V1804D) and instead found FGFR1 amplification and an FGFR1 fusion which may have been driving the tumor and are targetable by several FGFR inhibitors." (PMID 34504655, 2021). "FGFR1 protein expression was reported to be increased in uterine fibroids compared to the myometrium, and its expression appears to be correlated with the size of the tumor." (PMID 33807176, 2021). "Furthermore, elevated levels of FGFR1 and FGFR3 associated with tumor progression and drug resistance, also correlated with expression of c-MYC, another protein responsible for tumor angiogenesis." (PMID 34830951, 2021). "Regorafenib inhibits angiogenic (VEGFR-1–3, TIE2) and stromal (PDGFR-β, fibroblast growth factor receptor 1 or FGFR1) factors that promote tumor vessel formation and suppresses several oncogenic kinases (KIT, RET, RAF) and has shown promising results in advanced refractory CCA." (PMID 34068398, 2021). "Interestingly, PTX3 strongly reduced FGFR1 activation in both sulfobiotin+ endothelial cells and tumor cells as assessed by phospho-FGFR1 immunostaining." (PMID 34066669, 2021). "However, following this initial rapid reduction in tumor size, only the FGFR1 overexpressing tumors maintained a more solid mass which required two additional rounds of T-DM1 treatment to achieve complete tumor regression." (PMID 33479246, 2021). "Moreover, the miR-15a-5p level was increased and FGFR1 protein was downregulated in the CERS6-AS1-silenced tumor xenografts." (PMID 33581689, 2021). "Thus, FGFR1 is considered as an attractive tumor biomarker and several approaches for selective treatment of FGFR1 overproducing cancer cells have been developed, including cytotoxic conjugates with antibody fragments or natural ligands as targeting agents." (PMID 34635096, 2021). "In our previous study, we showed that tumours expressing FGFR1-4 are sensitive to infigratinib." (PMID 34156519, 2021). "In addition, overexpression of FGFR1 and IGFBP4 genes was found significantly associated with early tumor stage (i.e., tumor stage < = 2)." (PMID 34061869, 2021). "Moreover, ectopic overexpression of FGFR1 was sufficient to enhance tumor growth, diminish trastuzumab binding, and promote recurrence following T-DM1-induced MRD." (PMID 33479246, 2021). "Thus, suppression of FGFR1 expression by OC-X treatments was fundamental in reducing the MMTV-PyVT mouse tumor volume." (PMID 34069906, 2021). "Moreover, expression of FGFR1 is associated with transition to CRPC, and the FGF pathway can drive tumor progression in tumors refractory to AR-directed therapies." (PMID 33471819, 2021). "Given that zotatifin downregulates the protein expression of RTK oncogenic drivers, the anti-tumor activity of zotatifin (i.e., effect on proliferation and apoptosis) was tested in a panel of cancer cell lines that are driven by alterations in FGFR1/2 and HER2." (PMID 34900714, 2021). "Taken together, the positive ratios of FGFR1/2/3/4 were generally over 10% in most tumor types, indicating that right combination of FGFR1-4 genes might benefit patient enrollment in clinical trials in certain tumor types." (PMID 32596330, 2020). "In patient #5, all tumour components displayed the FGFR1 copy number gain." (PMID 32058674, 2020). "Notably, two of the unclassifiable LGNET with high tumor content (uLGNET #1 and #2) had genetic signatures of RGNT with FGFR1 kinase domain hotspot missense mutation in combination with PIK3CA or PIK3R1 mutation." (PMID 32859279, 2020).
tumor (continued). "Additionally, we calculated the (hypothetical) absolute copy numbers of FGFR1 based on the log2ratio and tumor fraction estimation from ctDNA." (PMID 32517171, 2020). "Two patients had FGFR1 copy number gains in at least one tumour component." (PMID 32058674, 2020). "Ultimately, the positive ratios of FGFR1/2/3/4 were generally over 10% in most tumor types." (PMID 32596330, 2020). "Since the detection of FGFR1 amplification in plasma critically depends on both the absolute copy number of the gene (amplification amplitude) and then tumor fractions, a generalized threshold for the detection could not be established." (PMID 32517171, 2020). "Interestingly, the positive ratios of FGFR1-4 in CHOL were all very high while only one or two FGFR genes were positively expressed in other types of tumor." (PMID 32596330, 2020). "Additionally, one other tumor (RGNT #5) harbored trisomy of chromosome 8 containing the FGFR1 locus, resulting in two copies of the mutant FGFR1 allele being present." (PMID 32859279, 2020). "The expressions of FGFR1-4 in MA-10 cells and inoculated MA-10 tumors were reduced after cordycepin exposure, indicating that cordycepin could reduce tumor growth through FGFR-signaling pathways." (PMID 33172093, 2020). "TMZ reduced tumour growth significantly in FGFR1 knockdown U87/TR tumours." (PMID 32181582, 2020). "Patients #3 and #5 had an FGFR1 copy number gain in at least one tumour component." (PMID 32058674, 2020). "Interestingly, MYC is expressed in 40% of FGFR1-amplified tumors and tumor cells co-expressing MYC and FGFR1 are more sensitive to FGFR inhibition." (PMID 33317057, 2020). "Without estrogen signaling, it is attractive to speculate that tumor progression may be driven by other signaling factors such as either FGFR1 signaling and/or LepR signaling." (PMID 33019728, 2020). "Moreover, high levels of FGFR1 were correlated with tumor size (P<0.01), tumor depth (P<0.01), lymph node metastasis (P=0.001) and clinical stage (P<0.01)." (PMID 31138759, 2019). "Our immunofluorescence and immunohistochemistry analysis demonstrates a high degree of FGFR1 expression in the solid epithelial cell clusters of post-IACC tumor tissues, which reinforced our proteomic data finding and led us to further investigate this marker in LGACC." (PMID 30728899, 2019). "Because the addition of the FGFR1 inhibitor AZD4547 actually led to downregulation of the tumor suppressor miR-214-3p in H1581 and DMS114 cells, we hypothesized that the downregulation of miR-214-3p partially accounted for the modest efficacy of AZD4547." (PMID 31492847, 2019). "Potency of 3D185 almost equal to that observed for FGFR1/2/3, suggesting that 3D185 may exert antitumor activity by simultaneously targeting the tumor microenvironment." (PMID 31438996, 2019). "FGFR1 overexpression antagonized the anti-tumor effects of miR-198 overexpression." (PMID 31138759, 2019). "This implies that patients with endocrine resistant ER-positive/FGFR1-amplified tumours may benefit from the treatment with combination of ER and FGFR antagonists." (PMID 31142340, 2019). "Immunohistochemical analysis of tumor tissues indicated an up-regulation of FGFR1 in tumor tissues." (PMID 31138759, 2019). "Furthermore, suppression of ectopic FGFR1 signaling reduces inflammation in the tumor microenvironment and reverses metabolic reprogramming of cancer cells, both of which have profound effects on anti-cancer chemotherapies and anti-checkpoint treatment." (PMID 30761180, 2019). "Gene expression levels measured relative to the adjacent normal cortex sample revealed numerous oncogenic driver genes with >2-fold higher expression in the tumour and clone samples, including genes encoding AURKA/B, CDK4/6, FGFR1, AKT1/2, MTOR, MET, PIK3C2A, WNT5A, SFRP4, and MYC." (PMID 30736342, 2019). "Both ADAM9 and FGFR1 are important factors in tumor development and metastasis induction." (PMID 31409686, 2019).
tumor (continued). "miR-133b, by targeting FGFR1, presents a plethora of tumor suppressor activities in OS cells." (PMID 30574019, 2018). "Samples with either TRPV4, KRAS, or FGFR1 mutations had strong phospho-ERK staining in a large component of the mononuclear cells in the tumor, while the multinucleated giant cells were negative, as expected." (PMID 30385747, 2018). "The remaining five mutation positive Group 1 tumours lacking a BRAF mutation possessed an FGFR1, NF1, ARID1B, HIST1H3B, and ATM mutations, respectively." (PMID 29058119, 2018). "We demonstrate that Vegfr2 gene dosage, but not synergy with endothelial Fgfr1 and Fgfr2, is critical for tumor growth and associated tumor angiogenesis." (PMID 30283071, 2018). "FGFR1 is expressed on a number of different cell types including tumor cells." (PMID 30484492, 2018). "Moreover, through the use of an in vivo mouse model with FGFR1-amplified BC primary xenograft (HBCx-3), the authors showed that the tumor regressed after treatment with 50 mg/kg of dovitinib, compared to mice treated with just a vehicle control (p < 0.001)." (PMID 30011957, 2018). "FGFR1 amplification has also been found in local and distant metastases suggesting a clonal event in tumor progression, therefore also suggesting that FGFR1 amplification occurs early in tumorigenesis and in turn, provides promise for treating patients with advanced disease." (PMID 29351293, 2018). "In order to determine whether copy number correlated with tumor stage, tumor stages 1–2 and 3–4 were grouped and compared to FGFR1 CN." (PMID 29351293, 2018). "Recently, it was suggested that glioneuronal tumours can be separated into two groups: one group enriched for BRAF mutations with an astrocytic expression phenotype and one group enriched for FGFR1 mutations with an oligodendrocyte precursor expression phenotype." (PMID 29963264, 2018). "We previously reported that FGFR1 inhibition reduces MPM tumor growth in vitro and in vivo." (PMID 29094504, 2018). "p38 can be activated by tyrosine kinase receptors (PDGF receptor, VEGF receptor, EGF receptor, FGFR1) to function as a positive regulator of tumor progression, mediating motility and invasion, suppressing apoptosis, stimulating the epithelial‐to‐mesenchymal transition in various cell types." (PMID 29463565, 2018). "Furthermore, we demonstrate that combined inhibition of two miR‐15/16 targets, FGFR1 and Bcl‐2, has synergistic effects on tumor cell growth encouraging further consideration as novel combination strategy in MPM." (PMID 29094504, 2018). "Interestingly, anti-tumor response (partial responses) was observed in 11% of patients with amplified FGFR1 LSQCCs." (PMID 30060526, 2018). "For the future, it will be necessary to determine whether FGFR1 inhibition-induced autophagy can be targeted for therapeutic gains using in vivo tumor models, particularly patient derived xenograft (PDX) models." (PMID 28558758, 2017). "We determined whether targeting downstream signaling implicated in FGFR1 effects on glucose metabolism potentiates the anti-tumor activity of FGFR1 inhibition in SQCLC." (PMID 29190880, 2017). "This patient's tumor demonstrated 8 mutations overall including alterations in the PI3K, MAPK pathways (mutations in FBXW7, FGFR1) with concurrent epigenetic and transcriptional deregulation, specifically ARID1A, ETV1 rearrangement, NOTCH1 APIP-NOTCH1 fusion, and MYST3 amplification." (PMID 28781987, 2017). "The PDECX model 1T0327 with overexpression of both EGFR and FGFR1 protein showed only modest tumor growth inhibition to theliatinib treatment suggesting that FGFR1 overexpression could diminish theliatinib efficacy." (PMID 28881608, 2017). "FGFR1 inhibition in cell lines and mouse models with FGFR1-amplified engrafted tumors suppressed tumor cell growth and induced apoptosis, suggesting that FGFR inhibitors may be an effective therapeutic option in SCCs with FGFR1 amplification." (PMID 29179482, 2017).
tumor (continued). "Therefore, FGFR1 immunohistochemical scoring was based on the presence of FGFR1-positive malignant cell clusters or larger tumor areas (i.e. diffuse staining), and scoring of individual cells was omitted in the analysis." (PMID 28468611, 2017). "Interestingly, treatment with a FGFR inhibitor AZD4547 induced rapid tumor regression, suggesting that FGFR1 overexpression was driving the tumor growth in the specific model." (PMID 28881608, 2017). "Further analysis basing on the different Lum subtypes revealed that FGFR1 correlated with the high pN (p = 0.023), pT stages (p = 0.003), large tumor size (p = 0.005), the presence of LVI (p = 0.010), p-cadherin (p = 0.028), SYN (p = 0.009) and SOX2 (p = 0.034) expression in Lum A subtype only." (PMID 26673008, 2016). "Bertotti et al35 recently carried out exome sequence and copy number analyses of both patient‐derived xenografts and patient tumours, to investigate the effects of mutations in ERBB2, EGFR, FGFR1, PDGFRA and MAP2K1 in relation to resistance to anti‐EGFR therapies." (PMID 26690310, 2016). "Analysis of tumour tissue at the time of treatment may reveal temporal heterogeneity in FGFR1 amplification and expression which alters the predicted response to FGFR inhibitors." (PMID 26905262, 2016). "Given the relevance of FGFR pathway in treatment resistance in luminal cancers, FGFR1 could be an important tumor biomarker and adverse prognostic factor potentially exploitable in the clinical management of luminal cancers." (PMID 26673008, 2016). "In a panel of sqNSCLC tumours 14.4% (13/90) were FGFR1 amplified by FISH." (PMID 26905262, 2016). "Finally, up-regulation of tumor FGFR1 expression and adaptation of bone micro-environment putatively contributed to therapy-resistance." (PMID 27105539, 2016). "This suggests that in tumour samples additional transcriptional and translational mechanisms may alter FGFR1 expression in amplified samples." (PMID 26905262, 2016). "Unlike FGFR1-3, where activating mutations and genetic amplifications are commonly associated with tumor progression, FGFR4 is rarely mutated in human cancers." (PMID 27192118, 2016). "FGFR1 expression was found to be associated with high pN (p = 0.042), pT (p = 0.037) stages and large tumor size (p = 0.017), but not with tumor grade, LVI, FF and patients’ age." (PMID 26673008, 2016). "As a result of its ability to inhibit both paracrine and autocrine functions of FGF8b, ARPCA exerts a significant inhibitory effect on FGFR1 phosphorylation, cell proliferation, angiogenic and tumorigenic activity of S115 tumor grafts in immunodeficient male mice." (PMID 25912421, 2015). "Recent studies have identified FGFR1 as a potential therapeutic target in SQCLC and have also demonstrated that amplification rather than mutation, represents the preferred mechanism of FGFR1 activation in this type of tumor." (PMID 26571236, 2015). "Moreover, FGFR1 inhibition can reduce proliferation and induce cell death in a variety of in vitro and in vivo tumor models harboring FGFR aberrations, and a growing number of research groups have selected FGFR1 as target for anticancer drug development." (PMID 25760077, 2015). "The somatic mutation profile of a tumour may contribute to this; for example, tumours harbouring or acquiring driver mutations in ESR1 or ERBB2 or amplifications at 8p12 (FGFR1) or 11q13 (CCND1) may be less responsive to targeted endocrine therapy." (PMID 25849106, 2015). "A tumor-initiating role of FGFR1 is also supported by studies from other cancer types." (PMID 26555375, 2015). "Increased FGFR1 copy number was observed in tumor tissue and PDXs." (PMID 26695660, 2015). "These analyses did not reveal significant associations between FGFR1 amplification and tumor phenotype or clinical outcome, neither in the subset of 202 ESCC, nor in the subset of 308 EADC." (PMID 26555375, 2015).
tumor (continued). "Importantly, analysis of 20 human BC samples revealed a five- to tenfold increase in the expression of FGFR1 to FGFR4 in tumor tissue as compared to matched normal tissue." (PMID 24618085, 2014). "Furthermore, two of the four patient tumor samples that displayed increased FGFR1 expression as compared to their matched surrounding normal tissues also demonstrated expression of the truncated FGFR1-β isoform." (PMID 24618085, 2014). "In addition to mutations, our data also demonstrated that these patient-derived NSCLC xenograft models carry gene amplifications in 4/10 models, including FGFR1 and cMET, which are known anti-tumor drug targets." (PMID 23842453, 2013). "On the surface our conclusions may seem to contradict previous work implicating FGFR1 in tumor cell proliferation in vitro and in primary tumor growth in vivo, especially because some of the experiments employed the same UM-UC3 cell line used here." (PMID 23468956, 2013). "Furthermore, the IHC results revealed that young affected patients (tumour diagnosis before 40 years of age) had an increased expression of FGFR1 in ULs (P = 0.0211)." (PMID 23483937, 2013). "For example, the discovery that FGFR1 may drive EMT through COX-2 activation suggests that COX-2 inhibition may be particularly beneficial in FGFR1-dependent invasive tumours." (PMID 22899908, 2012). "Interestingly, a bi-genic mouse line that has repressed FGFR2 combined with high FGFR1 activity (resembling our shR2 cells) shows enhanced tumor development in the prostate when compared to either repression of FGFR2 or overexpression of FGFR1 alone." (PMID 23185502, 2012). "Such interaction between NCAM and FGFR1 in the tumor microenvironment could potentiate the effect of FGFR1 expression and explain slow growth in the absence of FGFR1." (PMID 23185502, 2012). "As FGFR1 amplification has been reported in other tumor types, it may be the case that FGFR1 inhibition will be a successful therapeutic strategy in a variety of settings." (PMID 21666749, 2011). "We show that although there was very little effect of E7080 on the proliferation of a range of human tumor cell lines both their migration and invasion could be blocked at concentrations of E7080 that inhibited signaling through FGFR-1 and PDGFR-β." (PMID 21781317, 2011). "Given the close correlation for FGFR1 expression in our in vitro cell model and clinical tumour samples, as well as the specific mode of action for casodex (bicalutmide), we believe that the use of bicalutamide treatment is a valid in vitro tool for modelling androgen ablation." (PMID 21952621, 2011). "However, in this study we show that E7080 also has direct effects on tumor cells at concentrations that correlate with inhibition of other known targets, notably FGFR-1 and PDGFR-β." (PMID 21781317, 2011). "FGF2/FGFR-1 expression was localized in the cytoplasm of tumor cells." (PMID 21733164, 2011). "Furthermore, CISH analysis is relatively quick; in the present study, the whole analysis of FGFR1 amplification in a cohort of 880 patients took 2 weeks and, although only one tissue microarray core per tumour was analysed, 56% cases rendered optimal results." (PMID 17397528, 2007). "On multivariate Cox hazard analysis adjusted for tumour grade, size and lymph node status, for ER status, and for FGFR1 amplification, it was found that the FGFR1 amplification was a significant predictor of poor overall survival independent of the other known prognostic parameters (P < 0.04)." (PMID 17397528, 2007). "In the cohort of ER-positive tumours, no further associations between FGFR1 amplification and other clinicopathological parameters were found." (PMID 17397528, 2007). "Therefore, considering the combination of FGFR1 inhibitors with chemotherapy or immunotherapy may hold promise in achieving breakthroughs in anti-tumor activity." (PMID 40083325, 2025).